NQO1 (NAD(P)H quinone dehydrogenase 1)
Diseases named in the same sentence as NQO1 in open-access papers (continued):
Sharing a sentence is not in itself a finding about the gene and the disease.
cancer (continued). "The generation of NAD+ makes a strong, functional, yet indirect link between NQO1 and two very important cellular enzymes relevant for metabolism and metabolic reprogramming in cancer." (PMID 31470592, 2019). "In the present study, we evaluated compounds (1, 2, 4 & 5) isolated from B. cristata for their potential to induce the cancer chemopreventive marker enzyme NQO1 in murine Hepa-1c1c7 cells." (PMID 29788962, 2018). "Consistently, based on the different levels of the hNQO1 present in cancer and normal cells, the catalytic property of NQO1 has been recently exploited for the development of effective fluorescent probes for cancer detection." (PMID 30487423, 2018). "This futile cycle leads to an imbalance in the redox cycle and induces intracellular ROS production in NQO1-overexpressing cancer cells." (PMID 30584237, 2018). "Previous studies have suggested possible role of NQO1 suppression-enhanced chemosensitivity of the cancer cells." (PMID 29914576, 2018). "Previous studies have shown that NQO1 is one of the enzymes that play an important role in cancer cell migration and invasion of human aortic vascular smooth muscle cells." (PMID 29914576, 2018). "Fluorescence microscopy was used to demonstrate the potential of NQ-DCP fluorescent probe in the visualization of NQO1 in human cancer cells." (PMID 30487423, 2018). "A high-intensity unimodal distribution of signal was obtained for NQ-DCP activation in both NQO1-positive cancer cell lines." (PMID 30487423, 2018). "The reasons for NQO1 overexpression in cancers are still unclear, however, the elevated oxidative stress prevalent in most malignancies appears to be a link." (PMID 30487423, 2018). "NQO1 occurs in all tissues with the highest expression levels in epithelial, vascular endothelial, adipocytes, and cancer cells, especially liver tumors." (PMID 30595797, 2018). "Conversely, the expression of NQO1 has been found to be increased in cancers of lung, pancreas, breast, thyroid, stomach, and bile duct (CCA)." (PMID 29914576, 2018). "Developing an effective method for detecting NQO1 activity with high sensitivity and selectivity in tumors holds a great potential for cancer diagnosis, treatment, and management." (PMID 30487423, 2018). "Recent data revealed that reduced NAD phosphate (NAD(P)H):quinone oxidoreductase (NQO1) is a critical enzyme in bL-mediated inhibition of cancer proliferation." (PMID 30513573, 2018). "The isolated compounds were evaluated for their potential to induce the cancer chemopreventive enzyme marker NAD(P)H quinonereductase 1 (NQO1) in murine Hepa-1c1c7 cell model." (PMID 29788962, 2018). "The critical role of NQO1 as a promising target for cancer chemotherapy has been demonstrated in various studies." (PMID 29914576, 2018). "NQO1 is a two-electron oxidoreductase expressed in cancer tissue at levels 5- to 200-fold greater than in normal tissue." (PMID 30318513, 2018). "A C to T transition at position 609 in the NQO1 gene (OMIM: 125860) has been shown to alter the enzymatic activity of the enzyme and has been associated with increased risk to several cancers." (PMID 30160047, 2018).
cancer (continued). "Among phase I DMEs, the most studied carbonyl-reducing enzyme in relation to SFN is NAD(P)H:quinone oxidoreductase 1 (NQO1, also known as quinone reductase), which is recognized as an antioxidant, chemoprotective, and cancer-preventive enzyme." (PMID 29144397, 2017). "We characterize here interdomain site-to-site communication by which a common cancer-associated single nucleotide polymorphism (c.C609T/p.P187S) reduces the activity and stability in vivo of NAD(P)H:quinone oxidoreductase 1 (NQO1)." (PMID 28291250, 2017). "Since various tumours are upregulating the NQO1 levels, these chemotherapeutics are acting more specific on cancer than healthy cells." (PMID 28236663, 2017). "A 5.6-fold increase in NQO1 mRNA was reported to be present in PBMCs from cancer patients after 3 weeks of treatment with bardoxolone methyl." (PMID 28785379, 2017). "Within this group, β-lapachone, one of the most widely-studied naphthoquinones, has presented a potent cytotoxic activity against several human cancer cell lines, requiring for its bioactivation the enzyme NAD(P)H:quinone oxidoreductase 1 (NQO1)." (PMID 27384551, 2016). "The ultimate outcome is a futile redox cycle in NQO1-overexpressing cells, such as many cancer cells, which can culminate in formation of substantial reactive oxygen species (ROS), oxidative damage to DNA and single- and double-strand DNA breaks." (PMID 26822308, 2016). "More studies will be required to explore a dual function of NQO1 in different cancers and more importantly, how HIFs contribute to this dual function of NQO1 in tumorigenic progression." (PMID 27966538, 2016). "Conversely, increased expression of NQO1 can confer a growth advantage in some cancers such as melanoma, pancreatic adenocarcinoma, non-small cell lung cancer, and prostate cancer." (PMID 26822308, 2016). "An example of this class is Mitomycin C (MMC), which is reductively activated by nitroreductases, particularly the mammalian NQO1, whose concentration is up-regulated in cancer cells, making them more vulnerable to its action." (PMID 27457630, 2016). "Despite the fact that NQO1 has been reported to be highly expressed in numerous human cancers and our tumour xenograft experiments clearly argue that NQO1 is pro-tumorigenic, contradictory results on its biological roles in tumorigenesis have been reported." (PMID 27966538, 2016). "It is important to note that a short-term of β-lap exposure (2-8 h) triggers NQO1-mediated cancer cell apoptosis which can be eliminated by NQO1 inhibitor dicoumarol, while long-term exposure of β-lap (>12 h) induces nonselective damage to DNA or microtubules." (PMID 27566573, 2016). "We also observed that the cancer tissues expressing high NQO1 level also express higher-level of HIF-1α protein than tumours expressing relatively low NQO1." (PMID 27966538, 2016). "A mitochondria targeted AIE fluorophore was further decorated with an NQO1 cleavable masking unit and showed selective targeting to and activation in cancer cells resulting in bright AIE fluorescence and apoptosis triggered by mitochondrial dysfunction." (PMID 30034745, 2016). "Collectively, this study reveals a role for NQO1 in the oxygen-sensing pathway that regulates HIF-1α stability in cancers." (PMID 27966538, 2016). "The transcription factor Nrf2 binds to antioxidant responsive elements at the promoters of its target genes, such as HMOX1 and NQO1, to activate antioxidant gene expression, and renders cancer cells resistant to oxidative stress-mediated cell death." (PMID 27764794, 2016). "In some cases, inhibition of NQO1 can suppress cancer cell growth and potentiate chemotherapeutic cytotoxicity." (PMID 26822308, 2016).
cancer (continued). "Several studies have indicated that the phase II enzyme NQO1 catalyzes the metabolic detoxification of quinones and protects cells against chemical-induced oxidative stress and cancer." (PMID 25880877, 2015). "Taken together, we conclude that NQO1 plays a key role in the AMPK-induced cancer cell death in OGD through the CD38/cADPR/RyR/Ca2+/CaMKII signaling pathway." (PMID 25586669, 2015). "Together, these data indicate that NQO1 plays an important role in activating the AMPK pathway in cancer cells under OGD." (PMID 25586669, 2015). "The NQO1*2 polymorphism has been widely investigated but limited information is available on whether the NQO1*2 genotype is associated with specific types of cancers and whether it can be a useful prognostic indicator for efficacy of chemoprevention in specific cancer models." (PMID 27625902, 2015). "High-level expression of NAD(P)H: quinoneoxidoreductase 1 (NQO1) has been correlated with many types of human cancers, suggesting that NQO1 plays important roles in tumor occurrence and progression." (PMID 25880877, 2015). "BPTES pre-treatment sensitized a variety of NQO1-expressing KRAS mutant cancer cell lines to ß-lap, including lung, triple-negative breast, and additional PDA cell lines." (PMID 26462257, 2015). "β-lapachone (β-lap) is a promising anticancer agent by a mechanism of action highly dependent on the enzyme NQO1, a flavoprotein found overexpressed in various cancer cells." (PMID 25692465, 2015). "ß-Lap-exposed, NQO1+ cancer cells die by a unique caspase-independent programmed necrosis pathway, termed NAD+-Keresis8." (PMID 26602448, 2015). "Synergy with FK866+β-lap was tumor-selective, only occurring in NQO1-overexpressing cancer cells, which is noted in a majority (∼85%) of PDA cases." (PMID 25590809, 2015). "Regarding NQO1 mean expression in different lesions, statistically significant differences were seen between normal and each benign, borderline and malignant tumors (P = 0.005, P = 0.003 and P < 0.001 respectively)." (PMID 28983331, 2015). "The concept of reducing NAD+ pools in cancer cells to sensitize them to ROS-mediated cell death by β-lap is a novel strategy with potential application for pancreatic and other types of NQO1+ solid tumors." (PMID 25590809, 2015). "The fact that many cancer cells overexpress NQO1 has been exploited to develop novel therapies in which quinone compounds are reduced by Nqo1 to convert them into a toxic form that preferentially kills cancer cells." (PMID 26325183, 2015). "In contrast, alkaline comet assays revealed that the majority of DNA lesions immediately created in ß-lap-exposed NQO1+ cancers were DNA base and single strand break (SSB) lesions." (PMID 26602448, 2015). "β-Lap induces tumor-selective NAD+ depletion specifically in cancer cells that express high levels of NQO1." (PMID 25590809, 2015). "Non-overlapping specificities of FK866 for PDA tumors that rely heavily on NAMPT-catalyzed NAD+ synthesis and β-lap for cancer cells with elevated NQO1 levels affords high tumor-selectivity." (PMID 25590809, 2015). "Collectively, these results clearly demonstrate that OGD induces cell death by activating the CD38/cADPR/RyR/Ca2+/CaMKII/AMPK signaling pathway in NQO1-expressing cancer cells." (PMID 25586669, 2015). "Immunohistochemical stain showed that NQO1 and Nrf2 were highly expressed in carcinoma compared with normal and precancerous lesions." (PMID 28983331, 2015). "Then we study the relation of both NQO1 and Nrf2 expression and clinicopathological features of carcinoma cases." (PMID 28983331, 2015). "Regarding correlation between NQO1 and Nrf2 mean expression in different lesions, we found positive correlations between the two proteins especially in carcinomas." (PMID 28983331, 2015).
cancer (continued). "This quinone-containing compound, a substrate of NQO1 (NAD(P)H:quinone oxidoreductase, has shown anti-ageing as well as anti-cancer activities." (PMID 24533641, 2014). "Its anti-cancer activity is thought to be due to the two-electron reduction of β-lapachone catalyzed by NAD(P)H : quinone oxidoreductase (NQO1, DT-diaphorase), using NAD(P)H or NADH as electron source." (PMID 24505400, 2014). "In order to increase the clinical efficacy of β-lapachone, many methods have been examined to increase NQO1 expression or activity in cancer cells." (PMID 24505400, 2014). "In summary, NQO1 plays an important role in cytoprotection of cancer cells and modulates the sensitivity of chemotherapeutic agents, particularly in the high NQO1 expressing CCA cells." (PMID 24460787, 2014). "These functions have also led to the suggestion that NQO1 plays an important role in cancer chemoprevention." (PMID 24912939, 2014). "NAD(P)H-quinone oxidoreductase 1 (NQO1) is an antioxidant/detoxifying enzyme recently recognized as an important contributor to chemoresistance in some human cancers." (PMID 24460787, 2014). "Inhibition of NQO1 by dicoumarol suppressed cancer cell growth and potentiated the cytotoxicity of chemotherapeutic agents." (PMID 24460787, 2014). "Many drugs or treatments, such as cisplatin, heat shock, or radiation, can increase NQO1 expression or activity and facilitate the cytotoxicity of β-lapachone for various cancer cells." (PMID 24505400, 2014). "Although β-lapachone is very toxic for many cancer cells, cells with lower NQO1 levels are less sensitive." (PMID 24505400, 2014). "Because NQO1 is more highly expressed in various solid cancers than in normal tissues, β-lapachone can selectively kill these cancer cells." (PMID 24505400, 2014). "In all the four cancer tissues, Nrf2, Mrp1 and NQO1 showed significantly higher expression in contrast with the adjacent non-tumor tissue (* P<0.05 vs normal tissue, respectively)." (PMID 23667609, 2013). "Most studies with respect to ER and Nrf2 are focused on cancer and one report suggested that inhibition of ERα expression by the antiestrogen shikonin reverses the inhibitory effect of estrogen on NQO1 expression." (PMID 24260155, 2013). "The correlatively high expression of Nrf2 and its downstream genes, such as Mrp1 and NQO1, endues the malignant tumors with more power to survive when facing stimulus, such as chemo-drugs and radiation." (PMID 23667609, 2013). "Further work will be required to develop tumor type-specific NQO1-modifying agents for therapeutic intervention in cancers." (PMID 23874855, 2013). "To verify it, we studied the role of NQO1 in determining the anti-cancer effects of TSA against NSCLC." (PMID 22848731, 2012). "In normal tissues, NQO1 is expressed at relatively high levels in epithelial tissues, vascular endothelium and adipocytes while in cancer, NQO1 is expressed at high levels in many solid tumors including lung (NSCLC), breast and pancreatic." (PMID 22984577, 2012). "More importantly, the NQO1 dependent anti-cancer effect of TSA was further confirmed in the A549 tumor xenografts." (PMID 22848731, 2012). "The immunofluorescent staining of NQO1 was performed in many different human cell lines including cancer cell lines (pancreatic), immortalized cell lines (HBMEC, 16HBE) and primary cell lines (astrocytes, HUVEC)." (PMID 22984577, 2012). "β-Lapachone (Lap), a well studied NQO1 substrate, has been identified as a promising agent for various cancer therapy." (PMID 22848731, 2012). "In many cases, however, the reduction of quinones by NQO1 results in the formation cytotoxic hydroquinones and the bioactivation of quinone prodrugs by NQO1 has been utilized as a strategy to target NQO1-rich cancer cells." (PMID 22984577, 2012). "The NQO1 is expressed abundantly in various human solid cancers, including cancers of the breast, pancreas, lung, and colon." (PMID 21738692, 2011).
cancer (continued). "Although β-lap has been reported to induce apoptosis in various cancer types in an NQO1-dependent manner, the signaling pathways by which β-lap causes apoptosis are poorly understood." (PMID 21738692, 2011). "Better insights into the signaling pathways underlying the anti-cancer activity of β-lap will lead to advancement in treatment strategies of NQO1-directed cancer therapy using the novel drug." (PMID 21738692, 2011). "Because NQO1 is expressed more abundantly in a variety of human solid cancers than in normal tissues, β-lap can selectively kill human cancer cells." (PMID 21998736, 2011). "The anti-cancer activity of β-lap was known to be due to two-electron reduction of β-lap mediated by NAD(P)H: quinone oxidoreductase (NQO1, DT-diaphorase) using NADH or NAD(P)H as electron sources." (PMID 21738692, 2011). "We investigated a series of bioreductive benzoquinone mustard analogs as a model for NQO1 targeted individualized cancer chemotherapy." (PMID 21904446, 2009). "We made use of these findings to design a series of BM analogs with different affinities for activation by NQO1, as a model for developing NQO1 targeted individualized cancer chemotherapy." (PMID 21904446, 2009). "In this study, we investigated a series of BM analogs as a model for NQO1 targeted individualized cancer chemotherapy." (PMID 21904446, 2009). "Additionally, in this study, we proposed that activation of the NRF2/NQO1 pathway plays a key role in the cellular defense against oxidative stress in normal cells, whereas this response is impaired in cancer cells." (PMID 41531942, 2026). "Keeping in mind the presence of NQO1 in cancer cells, potential therapeutic treatments, such as the inhibition of NQO1, could/should be considered." (PMID 40002465, 2025). "Although its applicability in humans has to be still assessed, in vitro and vivo studies showed that it induces a growth defect in human cancer cell lines, leads to a significant decrease in growth rates in xenograft tumors and shows a potent inhibition of NQO1 in most tissues of mice." (PMID 40900796, 2025). "Despite the biological activities of this “cell protector,” NQO1’s antioxidant role was paradoxically demonstrated by the evidence demonstrating that genetic variation or disruption of the gene increased the likelihood of chemical-induced toxicity and cancer." (PMID 40008126, 2025). "Besides, it is important to bear in mind that HMOX1 and NQO1 are also two of the genes related to the main pathway deregulated by Ocoxin in all the four analyzed cancers: cell metabolism." (PMID 40176904, 2025). "This study, apart from addressing the problem of the NQO1 system as a cancer target, aimed to improve the availability of chrysin, which might be a challenge in designing and implementing new treatments." (PMID 40002465, 2025). "It has been proved that the probe has reliable diagnostic performance for imaging of cancer biomarkers, and could expressly detect the endogenous NQO1 activity in cancer tissues, and has great potential in intraoperative navigation." (PMID 40630553, 2025). "NQO1 homozygous individuals have a higher risk of benzene-induced hematotoxicity, acute nonlymphocytic leukemia, and other cancers, particularly leukemia." (PMID 41333220, 2025). "According to that, NQO1 may be crucial for the in situ activation of prodrugs that impact cancer cells with high levels of NQO1." (PMID 40002465, 2025). "NQO1 is already present at high levels in many human solid tumors or upregulated after induction of ROS and can be irreversible inhibited by the component ES-936, thereby potentially increasing oxidative stress within cancer cells." (PMID 40900796, 2025).